UGT1A1 (UDP glucuronosyltransferase family 1 member A1)
Diseases named in the same sentence as UGT1A1 in open-access papers (continued):
Sharing a sentence is not in itself a finding about the gene and the disease.
neutropenia (continued). "The combination test of UGT1A1*6 and UGT1A1*28 may prove to be a potential predictive biomarker of irinotecan-induced severe neutropenia in the Asian population." (PMID 26820647, 2016). "Among the 6 patients with wild-type UGT1A1*28, 1 and 4 patients experienced grade 4 leukopenia and neutropenia, and another patient experienced grade 4 thrombocytopenia, while among the 4 patients with heterozygous UGT1A1*28, 1 patient experienced grade 4 neutropenia." (PMID 26163340, 2015). "Additionally, the UGT1A1 genotype was the strongest predictor of severe neutropenia among factors included in the final prediction model." (PMID 25880011, 2015). "We developed and validated a clinically useful nomogram including UGT1A1 genotype and other non-genetic factors for predicting the risk of severe neutropenia in the first cycle of irinotecan-based chemotherapy." (PMID 25880011, 2015). "Subsequent to narrowing the factors by univariate analysis, multivariate logistic regression analysis only detected significant correlations between the occurrence of grade 4 neutropenia and the UGT1A1*6/*6 and *6/*28 groups (P=0.029; odds ratio, 6.90; 95% confidence interval, 1.22–38.99)." (PMID 24932285, 2014). "Furthermore, inherited genetic variations in UGT1A1, UGT1A7 and UGT1A9 are associated with grade 3/4 neutropenia." (PMID 25202427, 2014). "This indicates that factors other than UGT1A1 genetic variation may be involved in the occurrence of severe neutropenia." (PMID 24932285, 2014). "Patients with specific polymorphisms in UGT1A1 (UGT1A1*28) have impaired metabolism of SN38 and are predisposed to the major toxicities of irinotecan, which are diarrhoea and myelosuppression, particularly neutropenia." (PMID 22108516, 2012). "At the end of treatment, UGT1A1*28/*28 and all non-favourable genotypes were associated with haematologic and non-haematologic toxicities, severe neutropenia and diarrhoea and both." (PMID 20628391, 2010). "This study demonstrates that the ability of UGT1A1 to predict neutropenia is, at best, modest." (PMID 19639031, 2008). "Ability of UGT1A1 or baseline bilirubin to predict neutropenia is low and depends on regimen." (PMID 19639031, 2008). "However, both studies confirm that UGT1A1 testing has low sensitivity to predict severe neutropenia, as indicated by low R2." (PMID 19639031, 2008). "However, UGT1A1*28 is weakly correlated with diarrhea and neutropenia." (PMID 35340156, 2022). "Therefore, the potential impact of prophylactic G-CSF on the incidence of Grade 4 neutropenia is unknown in patients with UGT1A1-DV." (PMID 33386925, 2021). "Moreover, the study in Thai did not showed that UGT1A1*6 polymorphism significantly increased severe neutropenia." (PMID 32936306, 2020). "A retrospective study from Switzerland however could not confirm that UGT1A1*28 is the only risk factor for neutropenia and diarrhea." (PMID 35582146, 2019). "However, preemptive UGT1A1 genotyping is not yet endorsed by most national guidelines even though it is mentioned in the FDA package insert as a risk factor for neutropenia." (PMID 30646508, 2019). "Low UGT1A1 activity may result in diarrhea and neutropenia in a dose-dependent manner." (PMID 35582146, 2019). "This work successfully obtained multiple sets of PBPK model parameters that could reproduce the effects of genetic polymorphisms of UGT1A1 *28 and SLCO1B1 c.521T>C on the plasma concentration of SN-38 and side effects such as neutropenia and diarrhea using a VCS approach." (PMID 28397089, 2017). "Even though genotyping for the UGT1A1 polymorphisms could be important in order to prevent severe adverse effects such as neutropenia, it does not predict response to chemotherapy." (PMID 27563673, 2016). "In addition to UGT1A1 polymorphisms, the present study also identified age ≥70 years, coelomic fluid, and non-reduction in starting dose as risk factors for grade ≥3 neutropenia." (PMID 26710796, 2016).
neutropenia (continued). "However, factors other than the UGT1A1 genotype may contribute to irinotecan-induced severe toxicity such as neutropenia and diarrhoea." (PMID 25880011, 2015). "A haplotype including UGT1A1*6 and UGT1A7*3, noted in as many as 15% of Japanese patients, and UGT1A1*6 homozygosity, noted in 7% of Korean patients, were significantly associated with decreased glucuronosyltransferase activity for SN-38 and severe neutropenia." (PMID 18985035, 2008). "Among the 26 cases of UGT1A1*28 TA6/7, nine cases (34.6%) experienced grade 3~4 delayed-onset diarrhea and eight cases (30.8%) had grade 3~4 neutropenia." (PMID 32264830, 2020). "A meta-analysis involving 58 studies and 6087 patients has demonstrated the predictive value of UGT1A1*28: patients with TA6/7 and TA7/7 genotypes had a higher incidence of diarrhea and neutropenia than those with the TA6/6 genotype." (PMID 32357899, 2020). "Among the 86 patients, there were 60 cases of UGT1A1*28 TA6/6, of which seven cases (11.7%) experienced grade 3~4 delayed-onset diarrhea and nine cases (15.0%) had grade 3~4 neutropenia." (PMID 32264830, 2020). "UGT1A1*6, UGT1A7*3 and UGT1A9*1b should be monitored regularly to avoid the incidence of the severe neutropenia and diarrhea." (PMID 29609559, 2018). "The patients with UGT1A1*6 and UGT1A7*3 were prone to severe neutropenia, and the patients with UGT1A9*1b were prone to severe diarrhea." (PMID 29609559, 2018). "No grade III/IV diarrhea and neutropenia were found in the phase I study; the genetic examination of UGT1A1 was not planned." (PMID 39225504, 2024). "Febrile neutropenia was observed in 9.1% of patients in the heterozygous group, but not in the UGT1A1*1/*1 group (p = 0.20)." (PMID 36836140, 2023). "Although prescreening for UGT1A1 genotype is not required, individuals with known UGT1A1 homozygous *28/*28 genotype should be monitored closely for neutropenia and diarrhea, regardless of age." (PMID 36038616, 2022). "Our findings are in line with a prior report from a Japanese series where a non-significant increase of neutropenia incidence was also observed in patients carrying the UGT1A1*6/*28 heterozygous genotype, despite initially reduced irinotecan doses." (PMID 35207692, 2022). "Upfront irinotecan dose reductions do not reduce the burden of grade ≥ 3 neutropenia in UGT1A1*28 homozygous carriers." (PMID 35207692, 2022). "Although UGT1A1 polymorphisms are associated with the metabolism of irinotecan, their role as surrogate markers for FOLFIRINOX-induced neutropenia has not been confirmed." (PMID 35267552, 2022). "In two patients with UGT1A1 *1/*28, one experienced grade 4 neutropenia, while the other had no grade 3 or higher hematological toxicities." (PMID 34019214, 2021). "Two pharmacokinetic and one myelosuppression model were assembled to predict concentrations of irinotecan and its metabolite SN-38 given different UGT1A1 genotypes (poor metabolizers: CLSN-38: -36%) and neutropenia following conventional versus PGx-based dosing (350 versus 245 mg/m2 (-30%))." (PMID 33733372, 2021). "Despite it is not recommended routine UGT1A1 genotyping prior to starting sacituzumab, patients who are known to have reduced UGT1A1 activity should be monitored closely for severe neutropenia." (PMID 34834563, 2021). "Patients with homozygosity for UGT1A1*28 (*28/*28) or UGT1A1*6 (*6/*6) and heterozygosity for both UGT1A1*28 and *6 (*28/*6), which are associated with severe CPT-11-related neutropenia in Japanese patients, were coincidentally not enrolled in this study." (PMID 29464396, 2018). "Based on a previous study performed in our center, UGT1A1*6 and UGT1A1*28 were found to be related solely to irinotecan-induced severe neutropenia, and not to diarrhea, as most studies in Asia indicated." (PMID 28637434, 2017). "Both UGT1A1*6 and UGT1A1*28 related to G3–4 neutropenia, rather than delayed diarrhea, which was consistent with several large-sample analysis in Asia." (PMID 28637434, 2017).
neutropenia (continued). "Some clinical studies have reported that the UGT1A1*28 genotype does not affect the frequency of neutropenia, even if many other studies have reported this effect." (PMID 28397089, 2017). "In our study, there were no patients with UGT1A1*28 homozygotes or UGT1A1*28/UGT1A1*6 heterozygotes, though 2/3 of patients experienced grade 3–4 neutropenia in this study." (PMID 26808671, 2016). "In safety results, regardless of the UGT1A1 genotype, the subject incidence of severe neutropenia successively decreased in the second and third treatment cycles." (PMID 25880011, 2015). "Homozygous UGT1A1*28/*28 patients experienced haematologic toxicity, especially leucocytopenia and neutropenia, but because of the few events analysed the results were not statistically significant." (PMID 24834123, 2014). "In total, 17 single nucleotide polymorphisms were identified, five of which revealed an association with grade 3/4 neutropenia, including UGT1A7*4; however, UGT1A1*28 and UGT1A1*6, which have been previously reported, were not significant." (PMID 25202427, 2014). "In a multivariate logistic regression analysis, UGT1A1*28/*28 genotype was an independent predictive factor of haematologic toxicity and severe neutropenia with or without diarrhoea at the end of treatment." (PMID 20628391, 2010). "Moreover, the UGT1A1 genotype of the patient, and the activity of the gut microbial enzyme β-glucuronidase (GUS) have been suggested as biomarkers for the development of systemic (e.g. neutropenia) and gastrointestinal toxicity (e.g. diarrhea) respectively." (PMID 40597074, 2025). "However, as a substantial proportion of UGT1A1*28 homozygous patients do not experience grade ≥ 3 neutropenia, the management of neutropenia is considered more appropriate than prophylactic screening for patients with the UGT1A1 genotype." (PMID 37855848, 2023). "However, in the current study, no patients experienced severe neutropenia after the administration of PEG-G-CSF, even those with UGT1A1 *6 or *28 polymorphism." (PMID 32345249, 2020). "UGT1A1*28 TA6/7 type could increase the risk of grade 3~4 diarrhea (p = 0.027), which did not increase the risk of grade 3~4 neutropenia (p = 0.092)." (PMID 32264830, 2020). "Moreover, UGT1A1*28/*28 patients experienced leucocytopenia and neutropenia, although this is not statistically significant, probably due to the small number of the events analysed, as we only had four homozygous patients." (PMID 24834123, 2014). "In total, five SNPs were identified to reveal a correlation with grade 3/4 neutropenia, including UGT1A7*4; however, the correlation with UGT1A1*28 and UGT1A1*6, which has been repeatedly reported, was not significant." (PMID 25202427, 2014).
colorectal cancer (48 papers, 2008 to 2026). A primary or metastatic malignant neoplasm that affects the colon or rectum. "This literature review provides a comprehensive overview of UGT1A1 polymorphism in patients with colorectal cancer, including recent developments and the future landscape." (PMID 40432911, 2025). "All clinical-based studies reporting the UGT1A1 polymorphism in patients with colorectal cancer were identified and included in this review." (PMID 40432911, 2025). "A study evaluating the combination of irinotecan and platinum in the treatment of colorectal cancer reported an increased risk of severe diarrhea in patients with UGT1A1*6 alleles." (PMID 35340156, 2022). "The UGT1A1 genotype has previously been implicated as a prognostic marker for CPT-11 therapy in colorectal cancer cases." (PMID 32758288, 2020). "Recently, a study in Japanese colorectal cancer patients revealed that reduction of the initial irinotecan dose from 150 mg/m2 to 120 mg/m2 results in a safe and efficient therapy in UGT1A1 homozygote variant allele carriers." (PMID 35582146, 2019). "The analysis of a case-controlled study revealed increased risk of developing colorectal cancer (CRC) in individuals carrying UGT1A1*6 and UGT1A7*3 variants." (PMID 23468910, 2013). "We found that the overall adverse reaction spectrum was similar in pantumor species and colorectal cancer, while in colorectal cancer, the UGT1A1*6 mutation is highly correlated with the severity of diarrhea, and in pantumor species, among them, UGT1A1*28 is significantly related to mucositis." (PMID 35340156, 2022). "In colorectal cancer, good prognosis was evidenced in patients with the UGT1A1*28 polymorphism." (PMID 35340156, 2022). "Whether UGT1A1*28 genotype is associated with clinical outcomes of irinotecan (IRI)-based chemotherapy in Colorectal cancer (CRC) is an important gap in existing knowledge to inform clinical utility." (PMID 23516488, 2013). "The association of colorectal cancer (CRC) with UGT1A1*6 (G71R in exon-1), and UGT1A7*3 had been reported in Caucasoid, with an OR of 2.75; African Americans and American white; Chinese (Taiwan), with an OR of 2.75; and Chinese (mainland) with an OR of 4.9; and Chinese, with OR of 1.59." (PMID 23468910, 2013). "Notably, UGT1A1 has been implicated in resistance to a variety of drugs through this mechanism, and its polymorphisms are applied to guide dosing of irinotecan in colorectal cancer patients." (PMID 40332396, 2025). "Therefore, this study was designed to observe the difference in the adverse reaction spectrum to CPT-11 in panneoplastic and colorectal cancer patients with heterozygous mutation of UGT1A1 and the impact of dose reduction of CPT-11 on efficacy and prognosis in these patients." (PMID 35340156, 2022). "A multicenter phase III trial conducted by the Dutch Colorectal Cancer Group aimed to explore the connections between the UGT1A1-28 genotype and the following factors in 218 CRC patients treated with Irinotecan." (PMID 40432911, 2025). "To date, a wide range of studies have been conducted on how IRI affects colorectal cancer patients with various UGT1A1 genotypes but controversies exists regarding a clear pathway." (PMID 40432911, 2025). "Medication recommendations for CPT-11 in patients with colorectal cancer based on UGT1A1 guidelines." (PMID 39877392, 2024). "Medication recommendations for CPT-11 in patients with colorectal cancer based on UGT1A1 drug label." (PMID 39877392, 2024). "The levels of circulating bilirubin are associated with the prognosis of colorectal cancer (CRC), and the higher level of UGT1A1 single nucleotide polymorphism (SNP) predicts a 7% increase in CRC risk." (PMID 38693853, 2024). "In colorectal cancer, UGT1A1*6 is significantly related to diarrhea post CPT-11 use, efficacy and prognosis is not affected by various genotypes or CPT-11 dosage reduction." (PMID 35340156, 2022).
colorectal cancer (continued). "Most studies on the interaction of irinotecan with UGT1A1 have focused on patients with colorectal cancer (CRC) receiving the FOLFIRI (irinotecan, fluorouracil, and leucovorin) regimen." (PMID 35267552, 2022). "In colorectal cancer, the adverse reaction spectrum is similar to pantumoma except UGT1A1*6, which is significantly related to the severity of diarrhea." (PMID 35340156, 2022). "A follow-up phase II randomized trial compared the FOLFIRI regimen to a high-dose irinotecan FOLFIRI regimen in colorectal cancer patients, where UGT1A1 NMsin the high-dose FOLFIRI cohort received 300 mg/m2 irinotecan." (PMID 33805415, 2021). "UGT1A1 is also an efficacious and resistance-related enzyme of irinotecan in the treatment of colorectal cancer." (PMID 34034810, 2021). "The topoisomerase I-inhibitor irinotecan, widely used for the treatment of colorectal cancer in combination with 5-FU, is one of the drugs being metabolized by UGT1A1." (PMID 35582146, 2019). "In colorectal cancers, FOLFIRI containing CPT-11 was more effective in patients with UGT1A1*28/*28 polymorphism than UGT1A1-wild patients accompanied with a decrease of SN38 glucuronidation in the liver." (PMID 26482555, 2015). "Accurate description of current practice within advanced colorectal cancer (CRC) specialties were needed to inform an economic evaluation of the UGT1A1 pharmacogenetic test for irinotecan in the United Kingdom." (PMID 20661248, 2010). "UGT1A1 genotyping in the second-line treatment of colorectal cancer with high-dose Irinotecan administered once every 3 weeks, along with adjusting the initial Irinotecan dose for patients with the UGT1A1-7/7 genotype, resulted in cost savings for African and Caucasian populations." (PMID 40432911, 2025). "The 2010 guidelines from the Japanese Society for Cancer of the Colon and Rectum (JSCCR) address the treatment of colorectal cancer and emphasize the importance of understanding the role of the UGT1A1 gene in metabolizing the active form of SN-38 to its inactive form, SN-38 G." (PMID 40432911, 2025). "UGT1A1 metabolizes chemotherapeutic drugs such as irinotecan, used against colorectal cancer." (PMID 37079615, 2023). "Metastatic colorectal cancer patients with the UGT1A1 wild-type genotype can tolerate higher doses of CPT-11 and may obtain more favorable clinical results without significantly increased toxicity." (PMID 35340156, 2022). "Therefore, the aim of this study was to extensively investigate the association between genetic polymorphisms in CYP3A4/5, DPYD, UGT1A1, ABCB1, ABCC2, and ABCG2 and irinotecan induced-toxicity in cohort of Thai colorectal cancer patient." (PMID 32778670, 2020). "The purpose of this prospective study was to investigate whether UGT1A1*6 and *28 polymorphisms could be used to determine the initial dose level of CPT-11 to improve safety in patients receiving FOLFIRI for colorectal cancer." (PMID 26710796, 2016). "The goal of the present study was to investigate whether UGT1A1*6 and *28 polymorphisms could be used to determine the initial dose level of CPT-11 to improve safety in patients receiving FOLFIRI for colorectal cancer." (PMID 26710796, 2016). "Interestingly, overexpression of PXR in the colorectal cancer tissue samples was correlated with an increase in UDP glucuronosyl transferases UGT1A1, UGT1A9 and UGT1A10, and led to a marked chemoresistance to the active metabolite of irinotecan (CPT-11)." (PMID 21342487, 2011). "For example, the UGT1A1 gene is essential in metabolizing the colorectal cancer drug irinotecan." (PMID 20161780, 2010). "Thus, the UGT1A1 genotyping has been used to determine the personalized irinotecan dosage for the treatment of colorectal cancer patients." (PMID 20161780, 2010).